EFCC1 (EF-hand and coiled-coil domain containing 1)
Synonyms: C3orf73; CCDC48; FLJ12057
Tractability: No criterion of Open Targets' tractability assessment is met for any kind of drug.
Gene: Protein-coding gene on chromosome 3 (129,001,304 to 129,040,742, forward strand). Ensembl gene ENSG00000114654.
Subcellular location (Human Protein Atlas): Nucleoplasm; Cytosol
Gene Ontology:
Molecular function: calcium ion binding
Genetic constraint (gnomAD): Loss-of-function variants: 47 observed, 41.79 expected, observed/expected ratio (o/e) 1.12, 90% interval 0.89 to 1.43. The upper end of that interval is the gene's LOEUF score, 1.43, which puts it in group 5 of 6, group 1 being the genes least tolerant of losing a copy. Missense variants: 809 observed, 727.01 expected, observed/expected ratio (o/e) 1.11, 90% interval 1.05 to 1.18. Synonymous variants: 385 observed, 327.87 expected, observed/expected ratio (o/e) 1.17, 90% interval 1.08 to 1.28.
Homologues: Orthologues: chimpanzee EFCC1 (99% identical), macaque EFCC1 (96% identical), rabbit EFCC1 (77% identical), mouse Efcc1 (69% identical), rat Efcc1 (68% identical), guinea pig EFCC1 (66% identical), zebrafish eef1db (11% identical), zebrafish eef1da (10% identical), Drosophila melanogaster eEF1delta (9% identical), Drosophila melanogaster eEF1beta (8% identical), Caenorhabditis elegans eef-1B.1 (7% identical). Paralogues in human: EEF1D (14% identical), EEF1B2 (9% identical).
Diseases named in the same sentence as EFCC1 in open-access papers:
EFCC1 is named in the same sentence as 5 diseases in open-access papers, as found by Europe PMC text mining. Sharing a sentence is not in itself a finding about the gene and the disease. The quoted sentences say what the papers report.
lung adenocarcinoma (2 papers, 2022). A carcinoma that arises from the lung and is characterized by the presence of malignant glandular epithelial cells. "Finally, EF-Hand And Coiled-Coil Domain-Containing Protein 1 (EFCC1) has been studied in lung adenocarcinoma and shown, using immunohistochemical as well as RNA expression analysis, to be less prevalent in lung cancers and to predict poorer outcome." (PMID 35189960, 2022). "Finally, seven copper death genes related to lung adenocarcinoma were screened out, including ARHGEF39, EFCC1, SERPIND1, INSL4, ANLN, RHOV and CCL20." (PMID 36313444, 2022).
EFCC1 also shares sentences with these, for which no sentence is quoted: cancer (1 paper); glioma (1); head and neck squamous cell carcinoma (1); lung carcinoma (1).